KISS1 (KiSS-1 metastasis suppressor)
Diseases named in the same sentence as KISS1 in open-access papers (continued):
Sharing a sentence is not in itself a finding about the gene and the disease.
melanoma (continued). "KISS1 expression is detected in normal melanocyte and RGP melanomas, but its expression is lost in VGP and metastatic cells." (PMID 18211678, 2008). "Kisspeptin-1 (KISS1), a well-known metastasis suppressor protein, has been shown to markedly reduce pulmonary and intraperitoneal metastases in xenograft models of multiple cancers, such as melanoma, breast, and ovarian cancers." (PMID 41404065, 2025). "Pairs of melanoma cell lines sensitive and resistant to PLX4032, displaying different levels of KiSS1 and KiSS1R as well as a different pattern of KiSS1 release upon PL4032 exposure were considered to study whether the response to antitumor agents can be improved by the combination with KP54." (PMID 37790750, 2023). "Regarding this hypothesis, KISS1 inhibitor siRNA was transfected to melanoma cells with and without Let‐7i mimics." (PMID 34096173, 2021). "Finally, the kisspeptin 1 (KISS1) metastasis suppressor protein has been found to strongly inhibit pulmonary and intraperitoneal metastasis in xenograft models of various cancer types, including melanoma, breast and ovarian cancer." (PMID 31817646, 2019). "Only 1 year after the first paper on melanoma, Lee and colleagues conducted another study on breast cancer demonstrating that human breast carcinoma MDA-MB-435 cells transfected with KiSS-1 expression vector exhibit a lower metastatic, but not tumorigenic potential in comparison with control cells." (PMID 29760678, 2018).
breast carcinoma (45 papers, 2008 to 2026). "To further verify the biological role of KISS1 in the phenotypic behavior of breast cancer cells, we compared KISS1 loss‐ and gain‐of‐function cells for tumor formation in vivo by employing subcutaneous injections." (PMID 41523580, 2026). "CXCL12 downregulates the expression of Kiss1 in breast cancer cells, a gene associated with metastasis inhibition." (PMID 33096815, 2020). "So, even though several studies have identified the KiSS-1 gene as a metastasis suppressor in breast cancer, the existence of contradictory data underlines the need to better elucidate its biological role in this particular cancer." (PMID 29760678, 2018). "Our previous and current works pivotally connect two critical regulatory axes, GATA3/miR29b and miR29b/AF1q/TCF7/CD44/KISS1, associated with the Wnt pathway for breast cancer metastasis." (PMID 26079538, 2015). "Mitchell and colleagues found the loss of Kiss-1 gene expression in highly metastatic breast cancer cell lines." (PMID 25111296, 2014). "Also, KISS1 rs5780218 polymorphism has a statistically significant association with breast cancer risk." (PMID 32462300, 2020). "In contrast, the results obtained by another study of KiSS-1 expression in high-risk breast cancer patients on surgical samples support the hypothesis that the KiSS-1 gene is a metastasis suppression gene." (PMID 29662466, 2018). "To further investigate the biological functions and mechanisms of KISS1, we decide to carry out basic experiments using breast cancer cells." (PMID 41523580, 2026). "Here, we conducted a comprehensive investigation of KISS1 across various cancers, with a specific focus on breast cancer, using TCGA and GTEx datasets." (PMID 41523580, 2026). "Together, these results confirm the critical role of KISS1 in promoting the metastasis of breast cancer cells." (PMID 41523580, 2026). "Concordantly, PD‐L1 plays an important role in immunotherapy of breast cancers, reinforcing the potential role of KISS1 in the treatment of breast cancer." (PMID 41523580, 2026). "We observed a tissue context‐dependent role function of KISS1 in tumor metastasis, which exhibited suppressive effects in various tumors but promoted the metastatic phenotype in breast cancer." (PMID 41523580, 2026). "Intriguingly, our investigation also elucidated KISS1’s involvement in promoting breast cancer metastasis, thereby providing valuable insights into the molecular underpinnings of this process." (PMID 41523580, 2026). "In this article, we analyzed the potential role of KISS1 in pancancer metastasis using online databases from TCGA, GTEx, and GEO and verified the prometastasic role in breast cancer cells, which is unique to other cancer cells." (PMID 41523580, 2026). "Based on these results, we conclude a preliminary conclusion that KISS1 affects breast cancers differently from other cancers, which is consistent with previous studies." (PMID 41523580, 2026). "We used human MDA-MB-231 and SKBR3 breast cancer cell lines as positive controls to analyze KISS1 and KISS1R protein levels." (PMID 39404414, 2024). "miR-345 downregulates KISS1 which in turn leads to localization of breast cancer cells in the brain microenvironment." (PMID 39175471, 2024). "Another study reports that miR-345-mediated KISS1 transcriptional inhibition plays a role in promoting autophagy and invasiveness of breast cancer cells." (PMID 39175471, 2024). "Studies by Stark and colleagues have shown that, in breast cancer patients, KISS1 mRNA expression is lower in brain metastases compared to the primary tumours." (PMID 35955878, 2022). "While this study looked at the effects in HT-29 human colon cancer cells, KiSS1 is expressed in human breast cancer, leading to the conclusion that this therapy poses an opportunity to benefit breast cancer treatment specifically." (PMID 34960243, 2021).
breast carcinoma (continued). "The expression of Kiss1 in human breast cancer specimens inversely correlates with levels of matrix metalloproteinase-9 (MMP-9) and IL-8—genes implicated in metastatic invasion." (PMID 33096815, 2020). "This study contrasted the reports which supported the anti-metastatic potential of KiSS-1 in breast cancer." (PMID 29760678, 2018). "In other reported cases, the level of KiSS-1 mRNA and protein was higher in primary localized breast tumors than in breast cancer that was metastasized to other sites such as in the brain." (PMID 29662466, 2018). "Spanning a little over one decade, several studies have highlighted a detrimental role for KISS1/KISS1R in breast cancer." (PMID 30123188, 2018). "To date, in addition to playing a promoter role in breast cancer metastasis, KISS1 and KISS1R also appear to promote hepatic cell carcinoma." (PMID 30123188, 2018). "In support of these observations in breast cancer, treatment of ERα-positive breast cells with tamoxifen (an ER antagonist commonly used as an anti-cancer drug), increased KISS1 and KISS1R mRNA levels." (PMID 28422142, 2017). "As with anti-metastatic action in melanoma cell lines C8161 and MelJuSo, initially it was shown that KISS1 acts as a metastasis suppressor in human breast cancer cells, MDA-MB-435." (PMID 27101408, 2016). "In case of breast cancer, the data on potential action of KISS1 on invasiveness and metastasis is rather controversial." (PMID 27101408, 2016). "Recent studies revealed that KISS1 silencing increased cancer invasion and metastasis in breast cancer and bladder cancer through driving progression of epithelial-mesenchymal transition (EMT)." (PMID 27145368, 2016). "More recent studies highlighted the positive correlation of KISS1/KISS1R system with breast cancer progression and patient prognosis." (PMID 27101408, 2016). "Our previous study has indicated that Kiss-1 is the most important and independent impact factor for lymph node metastases in breast cancer." (PMID 25111296, 2014). "Originally identified as a metastasis suppressor gene in breast cancer and melanoma cell lines, the KISS1 gene products – kisspeptins – have been identified as the endogenous ligands for GPR-54, expression of which has been detected in pancreatic islets." (PMID 25401335, 2014). "On the other hand, studies in patients with breast cancer and hepatocellular carcinoma (HCC) have yielded opposite results, with a positive association between increased KiSS-1 levels and disease progression." (PMID 19154616, 2009). "Over-expression of KiSS1 in metastatic breast cancer cells or treatment of metastatic breast cancer cells with synthetic KiSS1 has been shown to reduce their metastatic potential." (PMID 18328103, 2008). "Furthermore, we validated the presence of posttranslational modifications of KISS1 in breast cancer, adding to our understanding of its role in tumorigenesis." (PMID 41523580, 2026). "Given the unique role of KISS1 in breast cancer, we further analyzed whether KISS1 may be an independent predictor of tumor metastasis in patients with breast cancer." (PMID 41523580, 2026). "KISS1 expression inhibits ATG5/7-related autophagy to suppress breast cancer brain metastasis." (PMID 36831154, 2023). "This study showed that treatment of ERα-positive MCF7 and T47D breast cancer cells with tamoxifen, a selective estrogen receptor modulator (with antagonistic role in breast tissue), stimulated KISS1/KISS1R expression, implicating that ERα signaling downregulates KISS/KISS1R levels." (PMID 30123188, 2018). "This may, in part, account for switching from the metastasis suppressor to metastasis promoter roles of the KISS1/KISS1R system in breast cancer." (PMID 30123188, 2018). "Interestingly, based on studies conducted on the human breast carcinoma MDA-MB-435 cell line, KISS1 was also reported to suppress breast cancer metastasis." (PMID 30123188, 2018).
breast carcinoma (continued). "Moreover, expression of KISS1 was higher in patients who had died from breast cancer than those who had survived." (PMID 27101408, 2016). "Along the KiSS-1 gene at least 294 SNPs have been described; however the association of these polymorphisms as genetic markers for metastasis in breast cancer studies has not been investigated." (PMID 25810563, 2015). "The aim of this study is to identify the rs5780218 (9DelT) and the rs12998 (E20K) KiSS1 polymorphisms and the allelic, genotypic, and haplotypic frequencies in Mexican general population (GP) and patients with benign breast disease (BBD) or breast cancer (BC)." (PMID 25810563, 2015). "In KiSS1 gene at least 294 SNPs have been identified, none previously associated with breast cancer." (PMID 25810563, 2015). "However, this may partly explain the crucial role of KISS1 in various cancers, including breast cancer." (PMID 41523580, 2026). "Besides the effect of endogenous KISS1 expression by breast cancer cells on their own vital parameters including proliferation and invasion, exogenous KISS1 may also alter invasive capacity of tumor cells." (PMID 27101408, 2016). "Here we describe two simple PCR-RFLPs protocols to identify the rs5780218 (9DelT) and the rs12998 (E20K) KiSS1 polymorphisms and the allelic, genotypic, and haplotypic frequencies in Mexican general population (GP) and patients with benign breast disease (BBD) or breast cancer (BC)." (PMID 25810563, 2015). "Indeed, patients who died of breast cancer had the highest expression of KISS1 mRNA." (PMID 21738726, 2011). "First, we explored KISS1 gene expression statuses in different breast cancer lines using the database from CCLE (Cancer Cell Line Encyclopedia) and found that nearly two‐thirds of the cell lines had a high KISS1 gene expression." (PMID 41523580, 2026). "However, some studies have shown that KISS1 may contribute to breast cancer metastasis." (PMID 41523580, 2026). "Further studies revealed that the suppression of KISS1/KISS1R signaling allows for the progression and metastasis of osteosarcoma, gastric, prostate, and breast cancer." (PMID 40430029, 2025). "Among these, KISS1 inhibits both proliferation and metastasis, and the Wnt ligand, WNT9A suppresses breast cancer cell proliferation and is a tumor suppressor of colorectal cancer." (PMID 35872983, 2022). "Previous studies have shown that KISS1 and KISS1R can suppress metastasis of numerous cancers, such as breast carcinoma, nasopharyngeal carcinom, bladder and ovarian cancer." (PMID 35117986, 2021). "Other genes selected by Rlogreg, namely KISS1, IGF2BP2, CALCA, PLA1A, and FAM171A1, have been reported to be related to breast cancer or other types of cancer." (PMID 32795265, 2020). "Our previous study has shown that knockdown of WASF3 upregulates KISS1, a metastasis suppressor, with concomitant reduced invasion and MMP9 activity in breast cancer cells." (PMID 30867003, 2019). "Taken together, these in vitro, animal model studies and clinical findings provide substantial support that KISS1 and KISS1R promote metastasis in breast cancer." (PMID 30123188, 2018). "Furthermore, a potential role of the KiSS-1/KiSS-1R complex has been proposed in the early stage of breast cancer development so this complex is not only involved in the advanced stages of the tumor, but could also represent a good target to hit tumors at an initial and final stage of development." (PMID 29760678, 2018). "Taken together, this data suggests that KISS1, KISS1R and AXL are upregulated in invasive breast cancer cells (Hs578T, MDA-MB-231, SKBR3FLAG-KISS1R), compared to non or weakly invasive breast cancer cells (SKBR3, MCF7 and T47D)." (PMID 28422142, 2017). "Despite well-documented studies showing anti-metastatic action of KISS1/KISSR signaling in numerous cancer types, the role of this system in breast cancer metastasis remained controversial." (PMID 27101408, 2016).
breast carcinoma (continued). "In addition, PKCα expression level correlates with estrogen receptor/progesterone receptor-negativity, higher tumor grade, increased Ki-67 positivity, and poor prognosis in human breast cancer, and the metastasis inhibitor KiSS1 may function in part by downregulating PKCα." (PMID 23613949, 2013). "Based on the use of established cell models of breast cancer and breast cancer patient data, several studies from our laboratories, and those of others would later show that KISS1 and its receptor KISS1R, in striking contrast to most cancers, promote breast cancer invasion, and metastasis." (PMID 30123188, 2018). "However, KISS1 has been reported to promote the metastatic capacity of estrogen receptor (ER) negative mammary epithelial and breast cancer cells." (PMID 41523580, 2026). "In fact a study conducted in 2005 by Martin and colleagues demonstrated that KiSS-1 may not be functioning as a metastasis suppressor in breast cancer cells." (PMID 29760678, 2018). "Interestingly, primary breast cancer Kiss-1 expression was not correlated with NSLN metastasis." (PMID 25111296, 2014). "Downregulation of KISS1 blocked TGFβ-mediated cancer cell invasion as well as MMP-9 expression and activity in TNBC cells, but not ERα-positive breast cancer cells." (PMID 30123188, 2018). "Previous work has shown that KISS1 and KISS1R levels are upregulated in invasive ERα-negative breast cancer cells (e.g., MDA-MB-231, Hs578T, SKBR3FLAG-KISS1R) in contrast to weakly invasive, ERα-positive luminal breast cancer cells (T47D, MCF7) or ERα-negative luminal SKBR3 cells." (PMID 32034133, 2020).
Obesity (36 papers, 2014 to 2026). Accumulation of substantial excess body fat. "Altered adipose tissue Kiss1 expression has been previously associated with obesity in rats and humans." (PMID 37035685, 2023). "In both congenital leptin deficiency and high-fat-diet-induced models of obesity, Kiss1-expressing neurons output is greatly reduced." (PMID 29643834, 2018). "Similarly, high‐fat‐diet‐induced obesity reduced hypothalamic Kiss1 mRNA expression and caused infertility in female mice." (PMID 34934398, 2022). "It was hypothesized that obesity causes an alteration in Kiss-1 gene expression, depending on the duration and degree of obesity." (PMID 31871451, 2019). "It exerts in vitro cultured hypothalamic cells for both the inhibition of GnRH release and Kiss1 mRNA production; taken together, this evidence underlines the link with negative energy balance and delayed puberty, as a specular model in comparison with obesity." (PMID 34684432, 2021). "It has been hypothesized that obesity acts via Kiss1 neurons to cause secondary hypogonadism." (PMID 25946091, 2015). "As a consequence of Kiss1 neuron dysfunction, obesity significantly affects GnRH-LH release patterns in females." (PMID 41321496, 2025). "In further support of this idea, studies in mice showed that liver Kiss1 expression increases in genetic models of obesity and type 2 diabetes (db/db and ob/ob mice)." (PMID 39404414, 2024). "We found that obesity-induced precocious puberty rats had an early first estrous cycle, increased hypothalamic mRNA expression of Kiss1, GPR54 and GnRH, and early gonadal maturation." (PMID 36568086, 2022). "Under conditions of energy excess, such as nutritional excess or early-onset obesity, SIRT1 is prematurely evicted from the promoter of KISS1, which promotes KISS1 expression, causing early puberty." (PMID 36046800, 2022). "Metabolic syndromes, such as obesity, are characterized by decreased hypothalamic and adipose tissue kisspeptin mRNA (KISS1) expressions." (PMID 35054403, 2021). "An ARC Kiss1 loss-of-function mouse model, induced by AAV1-DIO-GFP:tetanus toxin (TeTx) viral stereotaxic injection into adult Kiss1-Cre female mice, demonstrated an increase in body weight and obesity due to dysregulated feeding behavior." (PMID 34181485, 2021). "Our results identify SIRT1-mediated inhibition of Kiss1 as key epigenetic mechanism by which nutritional cues and obesity influence mammalian puberty." (PMID 30305620, 2018). "And in a genetic model of obesity, the leptin-deficient Ob/Ob mouse, ARC Kiss1 mRNA levels are reduced or unchanged as compared to control mice." (PMID 29740399, 2018). "In some conditions of energy imbalance, such as diabetes and obesity, very high energy reserves are present in the body, but due to the body’s inability to properly utilize them, an attenuation of Kiss1 mRNA expression was observed." (PMID 29643834, 2018). "Undernourishment and obesity/overnutrition affected hypothalamic Kiss1 expression at puberty in opposite directions: the former decreasing Kiss1 mRNA levels, the latter increasing gene expression." (PMID 30305620, 2018). "The hypothalamic expression of Kiss1 gene is significantly reduced not only in the rat model of diabetes but also in obesity rodent models." (PMID 29643834, 2018). "In summary, in the presence of genetic or obesity-induced concurrent insulin and leptin resistance, Kiss1 neurons are able to maintain reproductive function." (PMID 25946091, 2015). "Using a diet-induced model of obesity, the aim of this study was to evaluate the influence of obesity induced by a high-fat diet on the ovarian Kiss1 system and the ovulatory capacity in postpubertal rats." (PMID 25542298, 2014). "Impaired Kiss1/Kiss1r signalling leads to spontaneous development of obesity in adult female mice, with greater body weight, higher abdominal adiposity, reduced glucose tolerance, diminished thermogenic capacity within brown adipose tissue and a lower core body temperature." (PMID 37732890, 2023).